GLI2 (GLI family zinc finger 2)
Diseases named in the same sentence as GLI2 in open-access papers (continued):
Sharing a sentence is not in itself a finding about the gene and the disease.
hepatocellular carcinoma (21 papers, 2013 to 2025). A malignant tumor that arises from hepatocytes. "The mutation of GLI2 gene is one of the important reasons for abnormal activation in hepatocellular carcinoma." (PMID 40681919, 2025). "Glioma-associated oncogene 2 (Gli2), a primary transcriptional regulator of Hedgehog (Hh) signaling, is essential for hepatocellular carcinoma (HCC) growth and survival." (PMID 27036048, 2016). "In view of the important role of GLI2 in hepatocellular carcinoma, therapeutic strategies targeting GLI2 or its upstream and downstream regulators have become new therapeutic targets." (PMID 40681919, 2025). "In recent years, an increasing number of studies have shown that abnormal activation of GLI2 is closely related to the occurrence and development of hepatocellular carcinoma." (PMID 40681919, 2025). "In hepatocellular carcinoma, the promoter region of the GLI2 gene is demethylated, resulting in enhanced transcriptional activity of the GLI2 gene." (PMID 40681919, 2025). "Its interaction with GLI2 provides a new perspective for understanding the morbidity mechanism of hepatocellular carcinoma." (PMID 40681919, 2025). "Revealing this mechanism provides a new perspective for the morbidity mechanism and treatment strategy of hepatocellular carcinoma.LINC02560, a long non-coding RNA (lncRNA), is upregulated in hepatocellular carcinoma through interaction with GLI2 protein." (PMID 40681919, 2025). "In hepatocellular carcinoma, the upstream regulatory mechanism of GLI2 mainly involves the components of Hh ligands, receptors and transporters." (PMID 40681919, 2025). "The interaction between LINC02560 and GLI2 further enriches our understanding of the mechanism of morbidity in hepatocellular carcinoma." (PMID 40681919, 2025). "In particular, the interaction between LINC02560 and GLI2 provides a new perspective for understanding the morbidity mechanism of hepatocellular carcinoma.LINC02560 has been shown to regulate GLI2 through a variety of mechanisms." (PMID 40681919, 2025). "Accordingly, inhibition of GLI2 re-sensitizes to chemotherapy in hepatocellular carcinoma and lung cancer." (PMID 40133270, 2025). "The biological significance of GLI2 regulated by LINC02560 in hepatocellular carcinoma is also reflected in its impact on the tumor microenvironment." (PMID 40681919, 2025). "As a key transcription factor of Hh, GLI2 exerts its oncogenic effect by regulating the expression of downstream target genes in hepatocellular carcinoma.GLI2 can up-regulate the expression of genes related to cell proliferation, invasion and migration." (PMID 40681919, 2025). "In conclusion, LINC02560 regulates GLI2 through complex mechanisms and plays an important role in the occurrence and development of hepatocellular carcinoma." (PMID 40681919, 2025). "LINC02560, an lncRNA with abnormal expression in HCC, The mechanism of GLI2 regulation has a profound biological significance in the occurrence and development of hepatocellular carcinoma." (PMID 40681919, 2025). "In hepatocellular carcinoma, there is a complex interaction between GLI2 and others, such as Wnt, TGF-β, and Hippo." (PMID 40681919, 2025). "Increased levels of signaling pathway components (SMO, SHH, Gli1, Gli2) have been observed in hepatocellular carcinoma cells in culture and in cells from tumors excised from patients." (PMID 38927059, 2024). "The activation of glioma-associated oncogene family zinc finger 2 (Gli2), a central figure in Hedgehog (Hh) signaling pivotal for hepatocellular carcinoma (HCC) development, has been found to indirectly stimulate the expression of KIF20A through the activation of FOXM1." (PMID 39272816, 2024). "The role of Gli2 in the process of cellular dedifferentiation has also been described—with lower Gli2 expression in well-differentiated hepatocellular carcinoma cell lines compared to increased expression in poorly differentiated carcinoma lines." (PMID 38927059, 2024).
hepatocellular carcinoma (continued). "In hepatocellular carcinoma, the circular RNA circ_0036412 increases GLI2 (GLI Family Zinc Finger 2) expression, which promotes the Hedgehog pathway and cancer cell proliferation." (PMID 35884580, 2022). "Our unpublished data suggest that GLI2 functions as a downstream target of TGF-β/Smad3 in poorly differentiated hepatoma cells (Cancer Res 2020; 80 (16 Supplement): DOI: 10.1158/1538-7445.AM2020-6336)." (PMID 33440657, 2021). "Consistent with their mRNA levels, GLI1 and GLI2 protein levels were significantly increased in these four poorly differentiated hepatoma cell types." (PMID 32108992, 2020). "Up-regulation of JCAD inhibits the ability of LATS2 to phosphorylate YAP, thus elevating CCND1 and Gli2 expression to promote hepatoma cell proliferation." (PMID 32493490, 2020). "Down-regulation of Gli2 suppresses cell proliferation and sensitizes hepatocellular carcinoma cells to TRAIL-induced apoptosis." (PMID 32493490, 2020). "In Hepatoma cells, the treatment suppressed cell proliferation and decreased the protein levels of the GLI2 and ABCC1 transporter." (PMID 33396427, 2020). "Aberrant activation of GLI2 in hepatocellular carcinoma also involves abnormalities in signaling." (PMID 40681919, 2025). "This interaction makes the regulation of GLI2 in hepatocellular carcinoma more complex and diverse." (PMID 40681919, 2025). "In addition, LINC02560 regulation of GLI2 also affects the therapeutic effect and prognosis of hepatocellular carcinoma." (PMID 40681919, 2025). "Therefore, the study of GLI2 regulation by LINC02560 not only deepens our understanding of the mechanism of morbidity in hepatocellular carcinoma, It also provides important clues for finding new therapeutic targets and improving therapeutic effects." (PMID 40681919, 2025). "In addition to gene mutations, epigenetic modifications are also important factors contributing to the abnormal activation of GLI2 in hepatocellular carcinoma." (PMID 40681919, 2025). "The aim of this study was to investigate the expression and function of LINC02560 in hepatocellular carcinoma, and to elucidate the mechanism of its regulation of GLI2.Through this study, we expect to provide new ideas and methods for the treatment of hepatocellular carcinoma." (PMID 40681919, 2025). "Down-regulation of Gli2 plays an anti-cancer role in hepatocellular carcinoma." (PMID 32493490, 2020). "LINC02560 promotes the proliferation, invasion, and immune escape of hepatocellular carcinoma (HCC) by directly binding to GLI2 protein, regulating its epigenetic modifications, and interacting with other signaling pathways." (PMID 40681919, 2025). "As a regulator of GLI2, the expression level of LINC02560 is closely related to the therapeutic effect and prognosis of hepatocellular carcinoma." (PMID 40681919, 2025). "In hepatocellular carcinoma, LINC02560 regulates GLI2 through a complex mechanism." (PMID 40681919, 2025). "As in hepatocellular carcinoma, circ-ZNF609 inhibits miR-15a-5p/15b-5p expression and then elevates GLI2 (a key protein molecule concerning the Hedgehog pathway) expression, activating the Hedgehog pathway to promote hepatocellular carcinoma (HCC) proliferation and metastasis." (PMID 35938040, 2022). "However, the specific regulatory mechanism of GLI2 in hepatocellular carcinoma has not been fully elucidated, and its upstream regulatory factors also urgently need to be further studied." (PMID 40681919, 2025). "GANT61, a selective inhibitor of GLI1 and GLI2, was reported as a promising treatment for cancer in various tissues; however, the biological impact of GANT61 in hepatocellular carcinoma (HCC), especially in undifferentiated HCC cells, remains unclear." (PMID 32354204, 2020).
colon carcinoma (19 papers, 2010 to 2024). "For analyzing the effect of LA-induced cleaved GLI2 fragment on cancer cells, mouse orthotopic colon cancer models were employed." (PMID 35047127, 2022). "It has been reported that Hh signaling is blocked more efficiently by GANT61 at the level of GLI1/GLI2, which in turn induces DNA damage and cell death in human colon carcinoma cells, compared with the SMO inhibitor cyclopamine." (PMID 27349387, 2016). "Inhibition of GLI1/GLI2 by GANT61 or expression of the repressor GLI3 down-regulated the expression of NER-related genes in the human colon carcinoma HT29 cell line." (PMID 26197339, 2015). "GLI1 and GLI2 are constitutively activated in colon cancer cells by oncogenic signaling pathways upstream of GLI." (PMID 24962990, 2014). "Forced expression of GLI1 or a constitutively active mutant of GLI2 expression increased hTERT mRNA and protein in human colon cancer cells demonstrating HH/GLI-mediated regulation of hTERT expression." (PMID 24086482, 2013). "The relative potential of activating the other molecules between GLI1 and GLI2 was also measured and we found that GLI2 had higher number of downstream activated species in the colon cancer scenarios, as it had connection with GLI1." (PMID 23935937, 2013). "Blocking GLI1/2 activity reduced hTERT mRNA expression and the direct interaction between GLI1/GLI2 proteins and the hTERT promoter in human colon cancer cells." (PMID 24086482, 2013). "Further, hTERT promoter activity was significantly elevated in human colon cancer cells stably over-expressing GLI1 or GLI2." (PMID 24086482, 2013). "Chromatin immunoprecipitation with GLI1 or GLI2 antibodies precipitated fragments of the hTERT promoter in human colon cancer cells, which was reduced upon exposure to GANT61." (PMID 24086482, 2013). "Exogenous expression of GLI1 or GLI2 increased hTERT mRNA and protein expressions and hTERT promoter-luciferase activity in human colon cancer cells." (PMID 24086482, 2013). "Other recent studies confirmed the relevance of Hh signaling to cellular survival through the activation of GLI-1 and GLI-2 in human colon carcinoma cells using GANT 61, an inhibitor of the Hh pathway by targeting Gli." (PMID 23028941, 2012). "GANT61, and the classic SMO inhibitor cyclopamine (for comparison with other model systems), were evaluated in a panel of human colon carcinoma cell lines to determine the impact of inhibiting GLI1/GLI2 vs SMO." (PMID 21860067, 2011). "Inhibition of GLI1 and GLI2 by GANT61 induced > 80% cell death in 5/7 human colon carcinoma cell lines following 72 hr exposure (20 μM)." (PMID 21860067, 2011). "The requirement for both GLI1 and GLI2 for sustained proliferation and survival of human colon carcinoma cell lines in vitro, including HT29, was demonstrated using siRNA technology." (PMID 20957031, 2010). "Suppression of GLI1/GLI2 functions by a C-terminus truncated GLI3 repressor mutant (GLI3R), or by GANT61, a pharmacological inhibitor of GLI1/GLI2, reduced hTERT protein expression in human colon cancer, prostate cancer and Glioblastoma multiforme (GBM) cell lines." (PMID 24086482, 2013). "Expression of an N-terminus deleted constitutively active mutant of GLI2 (GLI2ΔN) increased hTERT mRNA and protein expression and hTERT promoter driven luciferase activity in human colon cancer cells while GANT61 inhibited hTERT mRNA expression and hTERT promoter driven luciferase activity." (PMID 24086482, 2013). "On the other hand, several studies in colon cancer show that the canonical Hedgehog pathway inhibits Wnt by regulating the expression of SFRP1 via its effector proteins, GLI1 and GLI2." (PMID 38474826, 2024). "Similar results are observed when a small molecule inhibitor of GLI1 and GLI2, GANT61, was used to block HH signalling in human colon carcinoma cell lines that express HH signalling components." (PMID 34445078, 2021).
colon carcinoma (continued). "Human colon cancer cells HT29 and SW480, exposed to GANT61 (20 μM), a small molecule inhibitor of GLI1 and GLI2, for 72 hr demonstrated reduced steady state levels of GLI1, GLI2 and hTERT proteins." (PMID 24086482, 2013). "It is evident that the drivers of HH signaling, the GLI genes, are critical to the survival of human colon carcinoma cells, and that DNA damage signaling downstream of GLI1/GLI2 inhibition is a critical regulator of cell death." (PMID 23097684, 2012). "In summary, we have compared gene expression profiles in two human colon carcinoma cell lines after targeting the function of the transcriptional regulators of HH signaling, GLI1 and GLI2, using the small molecule inhibitor GANT61." (PMID 20957031, 2010). "Other studies reported that GANT-61 inhibits GLI1/GLI2 in colon cancer cells that are resistant to the SMO inhibitors cyclopamine and GDC-0449; this observation suggests SMO-independent Hh signaling pathway activation in colon cancer." (PMID 26843616, 2016). "Using a genetic approach to suppress GLI1 and GLI2 using GLI3R, hTERT expression could also be inhibited in colon cancer cells." (PMID 24086482, 2013). "Therefore, it was clear that the abnormal activation of GLI proteins in colon cancer cell lines not only happened due to the abnormal expression of hedgehog ligands but also due to the effect of the interactions of RAS with GLI1 and GLI2." (PMID 23935937, 2013). "Thus, canonical activation of GLI1 and GLI2 via SMO is important for the survival and proliferation of human colon carcinoma cells in vivo." (PMID 20957031, 2010). "To identify unique downstream targets of the GLI genes that function in cellular proliferation in the context of colon carcinoma, we employed a small molecule inhibitor of both GLI1 and GLI2, GANT61, identified in a cell-based small molecule screen for inhibitors of GLI1-mediated transcription." (PMID 20957031, 2010). "Thus, using qRT-PCR, the expression of GLI1, PTCH1, GLI2 and SHH was determined in all human colon carcinomas examined." (PMID 20957031, 2010). "To identify unique downstream targets of the GLI genes, the transcriptional regulators of HH signaling, in the context of colon carcinoma, we employed a small molecule inhibitor of both GLI1 and GLI2, GANT61, in two human colon cancer cell lines, HT29 and GC3/c1." (PMID 20957031, 2010). "We have previously demonstrated rapid inhibition of binding of the GLI1 and GLI2 transcription factors to target gene promoters (1 hr), reduced reporter activity specific to GLI-luciferase, and rapid inhibition of gene transcription in human colon carcinoma cell lines in response to GANT61." (PMID 27863397, 2016).
prostate carcinoma (14 papers, 2009 to 2023). A carcinoma that arises from epithelial cells of the prostate gland. "The GLI (GLI1/GLI2) transcription factors have been implicated in the developmentand progression of prostate cancer although our understanding of how theyactually contribute to the biology of these common tumours is limited." (PMID 21633508, 2011). "Co-immunoprecipitation assays demonstrated the physical interaction between DAX1 and GLI1/GLI2, both in exogenous overexpression systems and in endogenous protein complexes from prostate cancer cells." (PMID 37504255, 2023). "Specifically, the protein expression of DAX1 and GLI1/GLI2 in different prostatic cancer specimens should be investigated." (PMID 37504255, 2023). "GLI2 expression directly enhances tumorigenesis in a model of myofibroblastic cells representing reactive stromal prostate cancer cells." (PMID 33494284, 2021). "Protein expression of the hedgehog signaling-pathway components SHH, PTCH1, GLI1, and GLI2 was also generally reduced in OLFM4-expressing prostate-cancer cells compared with control vector-transfected cells." (PMID 26581960, 2015). "Interestingly, DAX1 overexpression significantly inhibited Hh signaling by reducing GLI1 and GLI2 activity, prostate cancer cell proliferation, and viability." (PMID 37504255, 2023). "For example, GLI2, among resulted ARE-containing URGs in males (AR_21915096_ChIP-Seq_LNCaP-1F5_Human), is a TF in the Hedgehog pathway and has long been shown to be associated with prostate cancer tumorigenesis, among others." (PMID 36386839, 2022). "GLI2 (GLI family zinc finger 2): GLI2 is a primary mediator of the hedgehog signaling pathway, which has been reported in prostate cancer, and plays a critical role in the malignant phenotype of prostate cancer cells." (PMID 34290571, 2019). "In this study GANT61 abrogated GLI function in the nucleus, blocked both GLI1- and GLI2- mediated transcription, inhibited GLI1-DNA binding, and demonstrated anti-tumor activity against human prostate cancer xenografts." (PMID 24962990, 2014). "Similarly, blocking HH/GLI signaling in the prostate cancer cells C4-2, DU145 and PC3 also demonstrated decreased GLI1, GLI2 and hTERT protein expression." (PMID 24086482, 2013).
glioblastoma (13 papers, 2013 to 2024). The most malignant astrocytic tumor (WHO grade IV). "iPSCs induced with U87MG-CM were found to overexpress the GBM-specific marker glioma-associated oncogene (GLI2) which confirmed the conversion of iPSCs to glioblastoma cells(iPSC-GBM)." (PMID 37509281, 2023). "Interestingly in glioblastoma multiforme, GLI2 was among the super-enhancer-associated genes." (PMID 34333666, 2021). "To evaluate the effect of the identified GANT61 analogs on cancer cell viability, we first assessed the expression of GLI1 and GLI2 in two human glioblastoma cell lines, U87MG and T98G, previously shown to be GANT61-sensitive and GLI1-dependent." (PMID 38999049, 2024). "In our study, there was a tendency for MGMT overexpression in iPSCs induced with a U87MG monolayer CM and GLI2 was found to be over expressed, which confirmed these as iPSC-derived glioblastoma-like cells." (PMID 37509281, 2023). "PTEN-deficient glioblastomas expressed higher levels of GLI1 and GLI2 mRNA compared PTEN-expressing glioblastomas." (PMID 36010600, 2022). "Knockdown of PTEN by siRNA increased GLI1 and GLI2 mRNA transcription in PTEN-expressing glioblastomas, suggesting that the PI3K pathway regulated GLI1 and GLI2 expression." (PMID 36010600, 2022). "In an animal model with glioblastoma, the treatment with LDE225 decreased the tumor size with downregulation of GLI1, GLI2, PTCH1, and SMO." (PMID 34642915, 2022). "In human primary glioblastoma initiating cells, sonidegib reduces levels of GLI1, GLI2, PTCH1, and PTCH2 messenger ribonucleic acid (RNA) and protein, as well as GLI1 and GLI2 translocation into the nucleus." (PMID 32973971, 2020). "Silencing FGFR1 or FOXM1 downregulated genes involved in mesenchymal transition such as GLI2, TWIST1, and ZEB1 in glioblastoma stem-like cells." (PMID 30167084, 2018). "We performed a microarray analysis of genes that are differentially expressed in glioblastoma U87 cells overexpressing GLI2A, the active form of GLI2, relative to the control cells." (PMID 30305138, 2018).